PPM1D (protein phosphatase, Mg2+/Mn2+ dependent 1D)
Diseases named in the same sentence as PPM1D in open-access papers (continued):
Sharing a sentence is not in itself a finding about the gene and the disease.
colorectal cancer (15 papers, 2012 to 2023). A primary or metastatic malignant neoplasm that affects the colon or rectum. "PPM1D is a tumor suppressor gene and has been associated with various types of cancer, including breast, ovarian, and colorectal cancer; mutations of this gene may impact the ability of the body to repair damaged DNA33." (PMID 36882567, 2023). "The present study investigated PPM1D expression as a potential biomarker in colorectal cancer (CRC)." (PMID 25009596, 2014). "However, immunohistochemistry demonstrated a mainly nuclear expression of PPM1D in colorectal cancer." (PMID 25797250, 2015). "In context of the colon, WIP1 was found to be highly expressed in the stem cell compartment and loss of PPM1D suppressed APC(Min)-driven polyp formation in mice suggesting that WIP1 might be involved also in development of colorectal cancer." (PMID 28439615, 2017). "Of these, the PPM1D and PIGN genes have previously been identified as markers of colorectal cancer with a poor prognosis when highly expressed, whereas PLK2 has been described as a gene that promotes tumor growth in colorectal cancer." (PMID 35682850, 2022). "We employed the chemical inhibition of PPM1D with quantitative phosphoproteomics to identify the substrate spectrum of PPM1D after DSB induction by etoposide in human osteosarcoma (U2OS) and colorectal cancer (HCT116) cells." (PMID 36060052, 2022). "To investigate the generalizability of the identified PPM1D substrates beyond U2OS cells, we repeated the same phosphoproteomics screen in human colorectal cancer HCT116 cells." (PMID 36060052, 2022).
lymphoma (15 papers, 2012 to 2026). A malignant (clonal) proliferation of B- lymphocytes or T- lymphocytes which involves the lymph nodes, bone marrow and/or extranodal sites. "Nevertheless, the prevalence of PPM1D gene mutations varies in lymphoma and myeloma after HDCT/ASCT with lower prevalence in myeloma." (PMID 39194701, 2024). "In lymphoma patients, mutations in PPM1D have been correlated with worse response to standard systemic treatment, as well as shorter OS." (PMID 38132396, 2023). "Previous studies confirmed an increased prevalence of PPM1D mutations in chemotherapy-exposed lymphoma patients." (PMID 38132396, 2023). "The presence of PPM1D mutations has been correlated with reduced response to standard chemotherapy in lymphoma patients." (PMID 38132396, 2023). "Differences in the evolution of lymphoma and myeloma may cause the differential prevalence of PPM1D gene mutations in the two B-cell malignancies." (PMID 39194701, 2024). "Activating NOTCH1 mutations is one of the most frequent gene aberration found in human T-cell acute leukemia/lymphoma and the majority of these mutations are located in the PEST or heterodimerization domain similar to the Notch1 mutations detected in lymphomas from PPM1D-transgenic mice." (PMID 34771656, 2021). "We also detected frequent activating Notch1 mutations in lymphomas from PPM1D-transgenic mice." (PMID 34771656, 2021). "The next-generation sequencing performed on the sample confirms that the predominant T-cell clones in this lymphoma contained CAR-T cell fusion mRNA, with potential driver mutations found in TET2, BRAF (V600E), PPM1D, ATM, and RUNX1." (PMID 41509667, 2026). "If PPM1D gene mutations were caused by exposure to alkylating agents, the prevalence should be similar in all ASCT recipients including lymphoma and myeloma patients." (PMID 39194701, 2024). "In lymphoma patients, after several lines of chemotherapy and CAR-T cell therapy, the prevalence of PPM1D gene mutations was 20% and there was an association with inferior treatment outcomes." (PMID 39194701, 2024). "Other malignancies manifested in PPM1D-transgenic mice were leukemias/lymphomas (n = 9), different adenocarcinomas/adenomas (n = 18), and sarcomas (n = 4)." (PMID 34771656, 2021). "In this study, we investigated the clinical significance of PPM1D and the anti-lymphoma effects of GSK2830371 in MCL." (PMID 27626308, 2016). "PPM1D mRNA levels were compared across major lymphoma types (GSE2350)." (PMID 27626308, 2016). "We investigated whether GSK2830371-mediated PPM1D inhibition would enhance the anti-lymphoma effects of other compounds." (PMID 27626308, 2016). "In lymphoma patients, upon treatment with R-CHOP, expansion of PPM1D mutant clones has been reported and occurred more commonly than for other CH-related genes." (PMID 38132396, 2023).
leukemia (13 papers, 2015 to 2025). A malignant (clonal) hematologic disorder, involving hematopoietic stem cells and characterized by the presence of primitive or atypical myeloid or lymphoid cells in the bone marrow and the blood. "In summary, our investigation sheds light on the role of mutant PPM1D in modulating cellular responses to oxidative stress and DNA repair in leukemia cells, offering valuable insights into the underlying molecular mechanisms." (PMID 38896450, 2024). "Broadly, these results show that loss of SOD1 confers a disadvantage to leukemia cells that is markedly amplified in the context of the PPM1D-truncating mutation." (PMID 38896450, 2024). "In this study, we performed an unbiased, whole-genome CRISPR screen to investigate genes essential for cell survival in PPM1D-mutated leukemia cell lines." (PMID 38896450, 2024). "Genetic loss or pharmacologic inactivation of Ppm1d rendered primary leukemia cells more sensitive to the cytotoxic therapies used for AML, whereas activation of Ppm1d conferred a resistance phenotype." (PMID 37595362, 2023). "We further found that primary leukemia cells use Ppm1d to attenuate the cytotoxic effects of clinically used therapies and that genetic loss or pharmacologic inhibition of Ppm1d sensitizes mouse and human leukemia cells to these agents in vitro and in vivo." (PMID 37595362, 2023). "In contrast, leukemia cells with Ppm1d loss displayed an increased sensitivity to agents commonly used in the treatment of myeloid neoplasia including daunorubicin, cytarabine, decitabine, and azacitidine." (PMID 37595362, 2023). "Notably, loss of Ppm1d sensitizes leukemias to cytotoxic therapies in vitro and in vivo, even in the absence of a Ppm1d mutation." (PMID 37595362, 2023). "This raises the question of whether PPM1D mutations can be leukemia-founding mutations or if they represent a co-existing sub-clone, or even a bystander clone, and whether PPM1D mutations mechanistically contribute to driving leukemia development." (PMID 30388424, 2018). "A key question that arises is whether PPM1D mutations contribute to leukemia development." (PMID 30388424, 2018). "(A,B) Dose response curves for cell viability with SOD1-inhibitor (LCS-1) (A) or LCS-1 in combination with 0.25 uM NAC (B) in WT and PPM1D-mutant leukemia cell lines after 24-hours." (PMID 38896450, 2024). "This research not only enhances our understanding of PPM1D-mediated cellular responses, but also identifies potential therapeutic targets against PPM1D-mutant leukemia cells." (PMID 38896450, 2024). "Altogether, our results demonstrate a role for SOD1 in the survival of PPM1D-mutant leukemia cells and highlight a new potential therapeutic strategy against PPM1D-mutant cancers." (PMID 38896450, 2024). "To identify genes essential for PPM1D-mutant cell survival, we first created isogenic WT and PPM1D-mutant Cas9-expressing OCI-AML2 leukemia cell lines and selected two PPM1D-mutant clones for CRISPR screening." (PMID 38896450, 2024). "In this study, we performed whole-genome CRISPR/Cas9 screening to uncover synthetic-lethal partners of PPM1D-mutant leukemia cells." (PMID 38896450, 2024). "While its role in normal HSCs could portend toxicity issues, ablating Ppm1d sensitized MLL-AF9–expressing leukemia cells to cisplatin treatment, suggesting its therapeutic relevance in myeloid malignancy." (PMID 39087468, 2024).
leukemia (continued). "Taken together, these data suggests that PPM1D is a critical regulator of cytotoxic resistance in leukemia cells and inhibition of PPM1D, even in the absence of a PPM1D activating mutation, enhances the effects of cytotoxic therapy." (PMID 37595362, 2023). "Similarly, leukemias developed in Ppm1dT/+ mice were sensitive to inhibition of PPM1D in culture indicating that PPM1D may represent a pharmacological target in therapy-induced leukemias." (PMID 37709843, 2023). "To examine the effect of Ppm1d inhibition on leukemia therapy in vivo, we generated murine MLL-AF9+ leukemias that coexpress GFP and luciferase." (PMID 37595362, 2023). "To test if SOD1 deletion affected the fitness of PPM1Dmut vs WT leukemia cells in vivo, we transplanted PPM1D-mutant and -WT OCI-AML2 cells with or without SOD1 deletion into immunodeficient (NSG) mice." (PMID 38896450, 2024). "Ultimately, our data suggest that truncated PPM1D enhances abnormal growth of t-AML, and inhibition of PPM1D may represent a promising treatment strategy for a fraction of therapy-induced leukemias." (PMID 37709843, 2023).
lung carcinoma (13 papers, 2013 to 2025). "PPM1d-deficient neutrophils exhibit enhanced tumor infiltration and potently suppress lung cancer growth." (PMID 41254689, 2025). "To explore the role of PPM1D in lung cancer, we first detected the expression levels of PPM1D by real-time PCR and Western blotting in two lung cancer cell lines, A549 and H1299." (PMID 25123458, 2014). "In the present study, we found that PPM1D is expressed in two human lung cancer cell lines, A549 and H1299." (PMID 25123458, 2014). "This study provides evidence for the first time that PPM1D modulates lung cancer cell proliferation via cell cycle control." (PMID 25123458, 2014). "Further investigations should be conducted to unravel the regulatory mechanism of oncogenic phosphatase PPM1D in lung cancer cells." (PMID 25123458, 2014). "Knockdown of PPM1D in lung cancer cells resulted in decreased cell proliferation and impaired colony formation ability." (PMID 25123458, 2014). "To examine the function of PPM1D in lung cancer cells, we used lentivirus-mediated shRNA to knock down PPM1D expression in both A549 and H1299 cells." (PMID 25123458, 2014). "Taken together, we suggest that knockdown of PPM1D can suppress lung cancer cell growth via a blockade of cell cycle progression and mitosis." (PMID 25123458, 2014). "Recently, oncogenic PPM1D has been identified as a novel prognostic marker for the survival of patients with lung cancer." (PMID 25123458, 2014). "Furthermore, studies have confirmed that PPM1D is the target gene of mir-16 in the A459 lung cancer cell line." (PMID 38074028, 2023). "Here we show that mice with genetic knockout of Ppm1d or with conditional knockout of Ppm1d in the hematopoietic system, in myeloid cells, or in neutrophils all display significantly reduced growth of syngeneic melanoma or lung carcinoma tumors." (PMID 34131120, 2021). "This study reveals a potential therapeutic approach based on targeting PPM1D and further in vivo studies are planned to confirm whether it is a potent target for lung cancer treatment." (PMID 25123458, 2014). "Collectively, our results demonstrate that PPM1D is a key player in lung cancer cell growth." (PMID 25123458, 2014). "This study was designed to investigate the functional role of PPM1D in lung cancer cells." (PMID 25123458, 2014). "Therefore, to investigate the functional role of PPM1D in lung cancer, we employed lentivirus-mediated shRNA to knock down PPM1D expression in both cell lines." (PMID 25123458, 2014). "Therefore, in this study, we examined the role of PPM1D in cell growth via an RNAi lentivirus system in two human lung cancer cell lines, A549 and H1299." (PMID 25123458, 2014). "There results indicate that the lentiviruses containing PPM1D shRNA could efficiently suppress the expression of endogenous PPM1D in lung cancer cells." (PMID 25123458, 2014). "PPM1D silencing by RNAi may be a potential therapeutic approach for the treatment of lung cancer." (PMID 25123458, 2014). "However, the functional role of PPM1D in lung cancer remains unclear." (PMID 25123458, 2014). "In four out of five patients with lung cancer, PPM1D mRNA levels were significantly elevated in either TANs, neutrophils isolated from peritumor tissues (pTANs), or both, compared with the patient’s PBN PPM1D mRNA levels." (PMID 34131120, 2021).
myeloid neoplasm (12 papers, 2020 to 2025). Proliferation of myeloid cells originating from a primitive stem cell. "This study examined the genetic profiles of myeloid neoplasms following B-cell non-Hodgkin lymphoma, finding PPM1D mutations to be significantly more frequent than in myeloid neoplasms after solid cancers." (PMID 40227763, 2025). "PPM1D encodes a phosphatase that is recurrently activated across cancer, most notably in therapy-related myeloid neoplasms." (PMID 37595362, 2023). "This suggests the distinct role of PPM1D in myeloid neoplasms development after B-cell non-Hodgkin lymphoma." (PMID 40227763, 2025). "Further investigation is needed to elucidate the precise contribution of PPM1D and its interaction with other mutations in BNHL-related myeloid neoplasm development and prognosis." (PMID 40227763, 2025). "In other studies elucidating the mechanism of mutant PPM1D in clonal haematopoiesis and subsequent therapy-related myeloid malignancies, mutant PPM1D seemed to confer resistance to apoptosis in the context of genotoxic stress." (PMID 32526214, 2020). "Lastly, CH with PPM1D mutations has been implicated in therapy‐related myeloid neoplasms, but our myeloid NGS panel did not capture this mutation." (PMID 38497538, 2024). "Using these models to examine the role of Ppm1d in HSC biology and the therapy of myeloid malignancies, we found that despite being an important regulator of HSC fitness, PPM1D is also a therapeutic target to augment the efficacy of cytotoxic chemotherapy and radiation." (PMID 37595362, 2023).